TRPM4 (transient receptor potential cation channel subfamily M member 4)
Diseases named in the same sentence as TRPM4 in open-access papers (continued):
Sharing a sentence is not in itself a finding about the gene and the disease.
Cerebral ischemia (5 papers, 2017 to 2024). Restriction of arterial blood supply to the brain associated with insufficient oxygenation to support the metabolic requirements of the tissue. "Transient Receptor Potential Melatonin 4 (TRPM4) is upregulated concomitantly with SUR1 after cerebral ischemia, during which SUR1 binds to it to form SUR1-TRPM4, an octameric monovalent cation channel." (PMID 38808718, 2024). "In addition to TRPM4/SUR-1-mediated channels, Adenosine receptor-1 and -3 (A1R, A1e) agonists have been shown to be neuroprotective in cerebral ischemia and are expressed in A2B5(+) glia, which include astrocytes." (PMID 36555246, 2022). "TRPM4 is a calcium-activated nonselective cation channel that is expressed de novo after brain ischemia and injury." (PMID 28235044, 2017).
hemorrhage (5 papers, 2020 to 2024). Loss of blood from the vascular compartment to the exterior or into nonvascular body space as a result of rupture or severance of the blood vessels. "This genetic association study examines the association of DNA sequence variability in ABCC8 and TRPM4 with intraparenchymal hemorrhage progression in patients with severe traumatic brain injury (TBI)." (PMID 34309670, 2021). "Intraparenchymal hemorrhage progression models containing clinical covariates were outperformed by adding significant ABCC8 and TRPM4 genotypes." (PMID 34309670, 2021).
ventricular fibrillation (5 papers, 2018 to 2024). A disorder characterized by an electrocardiographic finding of a rapid grossly irregular ventricular rhythm with marked variability in QRS cycle length, morphology, and amplitude. "In the present study, we identify and characterize four novel TRPM4 variants found in patients with CHB or ventricular fibrillation." (PMID 29568272, 2018). "A developed ventricular fibrillation and idioventricular rhythm had been recorded in overexpression of TRPM4." (PMID 33959666, 2021).
colon cancer (4 papers, 2018 to 2022). "TRPM4 encodes a calcium-activated ion channel, which, in a human colonic cancer cell line, controls calcium-mediated secretion of MUC2, a major component of intestinal mucus barrier." (PMID 35158942, 2022). "The result of MEXPRESS analysis also showed that the mRNA expression level of TRPM4 was much lower in colon cancer samples than those in control samples (p=3.13e-16)." (PMID 36147460, 2022). "The results in the human colonic cancer goblet cell line (HT-29-18N2) showed that TRPM4 protein controls calcium-mediated secretion of MUC2 and MUC5AC in conjunction with a Na+/Ca2+ exchanger NCX." (PMID 35158942, 2022). "TRPM4 contributes to both mucin 2 and MUC5AC secretion in HT29-18N2 colonic cancer cells, where a Na+/Ca2+ exchanger 2 works in concert with TRPM4." (PMID 35056097, 2021). "Consistently, the role of TRPM4 in the regulation of β‐catenin signaling through GSK‐3β has been described in a colon cancer cell study." (PMID 28614631, 2018).
conduction disorders (4 papers, 2014 to 2021). "In the present study, we theoretically investigated the gating kinetics of a gain-of-function mutant of TRPM4 ‘E7K’ to show its pathophysiological significance in conduction disorder by means of gating analysis and numerical simulation." (PMID 34445219, 2021). "Another major finding of our study was the occurrence of multilevel conduction disorders in Trpm4-/-mice, suggesting that the TRPM4 channel plays a role in conduction both in the suprahisian and infrahisian territories as previously hypothesized." (PMID 25531103, 2014).
diabetes (4 papers, 2019 to 2022). "The expression trends of TRPV1 and TRPM4 in the patients with diabetes are similar to the patients with obesity." (PMID 34512754, 2021). "It has been reported that the dysfunction of the TRP ion channel (TRPV4, TRPV1, TRPM4, and TRPM) is considered to be related to obesity or diabetes, and these disorders are related to appetite, insulin secretion, and autoimmune response." (PMID 34512754, 2021). "In addition, we also found that TRP ion channel family genes (TRPV4, TRPV1, TRPM4, and TRPM5) related to obesity or diabetes were highly expressed in HBV-related HCC." (PMID 34512754, 2021).
edema (4 papers, 2021 to 2023). An abnormal accumulation of fluid beneath the skin, or in one or more cavities of the body. "Although cerebral edema was markedly alleviated 3 days after SE after glibenclamide and Trpm4–/– interventions, glymphatic function had yet to recover at this time point." (PMID 34494549, 2021). "Moreover, when cerebral edema was alleviated by glibenclamide treatment or genetic deletion of Trpm4, post-SE glymphatic system function recovered earlier, along with fewer p-tau–deposited neurons and neuronal degeneration and better cognitive function." (PMID 34494549, 2021). "Overall, downregulation of PN production and blockade of non-selective cation channels (TRPC6 and TRPM4) could relieve pulmonary edema in ARDS." (PMID 35794575, 2022).
epilepsy (4 papers, 2023 to 2026). A brain disorder characterized by episodes of abnormally increased neuronal discharge resulting in transient episodes of sensory or motor neurological dysfunction, or psychic dysfunction. "Furthermore, we showed that TRPM4 contributes to mossy cells death following status epilepticus and therefore modulates seizure susceptibility and epilepsy-related memory deficits." (PMID 37101159, 2023). "Blood and brain tissues were collected for biochemical assays (SUR1, TRPM4, IL-1β, IL-6, TNF-α, TAS, TOS, OSI, thiol-disulfide homeostasis), histological analyses (H&E, Cresyl Violet, and 8-OHdG immunostaining), and qRT-PCR of epilepsy-related miRNAs." (PMID 41718951, 2026). "On the contrary, NOR test showed no deficit in chronically epileptic mice neither in WT nor in Trpm4−/− mice indicating that this type of contextual memory is not effected in our IHKA epilepsy model." (PMID 37101159, 2023).
Heart block (4 papers, 2019 to 2025). Impaired conduction of cardiac impulse occurring anywhere along the conduction pathway. "Because other TRPM4 mutations in humans have been associated with familial heart block, we performed electrocardiograms in our mutant mice and found no abnormalities compared to WT siblings (data not shown)." (PMID 36341417, 2022). "A mathematical simulation suggested that heterogenous overexpression of TRPM4 will lead to conduction abnormalities, including all degrees of heart block (Type 1, 2, 3)." (PMID 31316392, 2019).
left ventricular hypertrophy (4 papers, 2021 to 2022). Enlargement of the LEFT VENTRICLE of the heart. "The same group had previously demonstrated the role of TRPM4 as a positive regulator of left ventricular hypertrophy induced by pressure overload; however, only recently were able to address the TRPM4 channel activity to a downstream effect of Piezo1." (PMID 35897650, 2022). "Note that left ventricular hypertrophy appeared in Trpm4−/− mice compared to Trpm4+/+ animals, as already reported in this mouse strain, but was not affected by irradiation." (PMID 36139640, 2022). "The authors reported left ventricular hypertrophy due to hyperplasia during the proliferative stage in Trpm4−/− mice." (PMID 33810249, 2021). "In contrast, TRPM4 can act as a positive regulator of pressure-overload induced left ventricular hypertrophy as selective deletion of TRPM4 in mouse cardiomyocytes resulted in an approximately 50% reduction of left ventricular hypertrophy induced by transverse aortic constriction." (PMID 35056097, 2021).
melanoma (4 papers, 2017 to 2022). A malignant, usually aggressive tumor composed of atypical, neoplastic melanocytes. "In a B16-F10 melanoma model, these mutations diminishes TRPM4-dependent focal adhesion, disassembly rates and cell invasion effects, confirming the TRPM4 channel as an adhesome component." (PMID 36844925, 2022).
right-bundle branch block (4 papers, 2020 to 2025). "A study in 160 unrelated probands identified multiple TRPM4 variants associated with right-bundle branch block and isolated AV block, signifying the role of TRPM4 in cardiac conduction." (PMID 33868385, 2021).
Sepsis (4 papers, 2018 to 2024). Sepsis is defined as life-threatening organ dysfunction caused by a dysregulated host response to infection. "The other TRP family member, TRPM4, controls M/MΦ survival in sepsis." (PMID 29928281, 2018). "The knockout of the TRPM4 gene increases the mortality in a murine model of LPS-induced sepsis." (PMID 29928281, 2018). "Additionally, TRPM2 and TRPM4 channels have been shown to enhance bacterial clearance and regulate inflammatory responses in CLP-induced sepsis." (PMID 38731999, 2024).
status epilepticus (4 papers, 2021 to 2025). Status epilepticus is defined as a continuous seizure lasting more than 30 min, or two or more seizures without full recovery of consciousness between any of them. "In a rat model of status epilepticus, SUR1 and TRPM4 protein and Abcc8/Trpm4 mRNA expression was increased within 6 h and persisted for 3 and 7 days, respectively." (PMID 34769328, 2021).
atrial fibrillation (3 papers, 2012 to 2023). A disorder characterized by an electrocardiographic finding of a supraventricular arrhythmia characterized by the replacement of consistent P waves by rapid oscillations or fibrillatory waves that vary in size, shape and timing and are accompanied by an irregular ventricular response. "TRPM7, albeit much less abundant in the atrium than TRPM4, is significantly upregulated in human atrial myocytes isolated from the patients with atrial fibrillation." (PMID 37511555, 2023). "We finally determined whether TRPM4 and TRPM7 channel protein expression would be altered in atria from patients with atrial fibrillation." (PMID 22802050, 2012). "TRPM7 channel protein expression was increased by 71.5 ± 12.8% in atria of patients with atrial fibrillation (P < 0.01 vs. sinus rhythm), while no change was seen for TRPM4 channel protein expression in atria of patients with atrial fibrillation (P = NS)." (PMID 22802050, 2012). "TRPM7, but not TRPM4, is upregulated in atria of individuals with atrial fibrillation." (PMID 22802050, 2012). "Interestingly, TRPM7, but not TRPM4, is markedly upregulated in human atria from patients with atrial fibrillation." (PMID 22802050, 2012). "However, it is unknown whether there is any potential contribution of TRPM4 channels to atrial fibrillation since no change in channel protein expression was observed in atrial tissues from patients with atrial fibrillation." (PMID 22802050, 2012). "No significant change was observed in TRPM4 protein, while remarkable increase was observed in TRPM7 protein in the three atrial samples from patients with atrial fibrillation." (PMID 22802050, 2012).
brain injury (3 papers, 2022 to 2026). Acute and chronic (see also brain INJURIES, CHRONIC) injuries to the brain, including the cerebral hemispheres, CEREBELLUM, and brain STEM. "In vivo studies have noted that glibenclamide-mediated inhibition of the SUR1/TRPM4 reduces brain edema and brain death after ischemic brain injury." (PMID 38808718, 2024). "Collectively, our findings corroborated that TRPM4 is the most likely regulator of the neuroprotective impact of FFA on CA/CPR-induced brain injury." (PMID 36050694, 2022).
Cognitive impairment (3 papers, 2021 to 2025). Abnormal cognition is characterized by deficits in thinking, reasoning, or remembering. "Previous research has shown that the inhibition of TRP channels, including TRPV2 and TRPM4, can mitigate cognitive deficits in a range of disease contexts models." (PMID 40340504, 2025). "Post-SE cognitive impairment was improved after genetic deletion of Trpm4 and glibenclamide treatment." (PMID 34494549, 2021).
COVID-19 (3 papers, 2023 to 2025). A disease caused by infection with severe acute respiratory syndrome coronavirus 2. "Markers of BBB dysfunction such as SUR1 and TRPM4, were increased in endothelial cells in COVID-19 brains." (PMID 37573554, 2023).
dilated cardiomyopathy (3 papers, 2014 to 2025). Cardiomyopathy which is characterized by dilation and contractile dysfunction of the left and right ventricles. "M1, associated with dilated cardiomyopathy and cardiac muscle contraction, contained enhanced proteins like Myl4, Trpm4, Irf3 in LV." (PMID 39921206, 2025). "To determine if the LV hypertrophy in Trpm4-/- mice could be a first step to dilated cardiomyopathy (DCM), we followed the mice over time by echocardiography." (PMID 25531103, 2014).
endothelial dysfunction (3 papers, 2021 to 2025). In vascular diseases, endothelial dysfunction is a systemic pathological state of the endothelium (the inner lining of blood vessels) and can be broadly defined as an imbalance between vasodilating and vasoconstricting substances produced by (or acting on) the endothelium. "In conclusion, appropriate levels of TRPM4 may be beneficial and help to avoid endothelial dysfunction during inflammatory diseases." (PMID 35056097, 2021). "In addition, transient receptor potential melastatin 4 (TRPM4), a non-selective cation channel, plays a significant role in endothelial dysfunction caused by various factors related to cardiovascular diseases." (PMID 38269270, 2024). "In contrast, FA-induced increases in TRPM4 expression and activation of TRPM2 channels, likely in response to FA-induced oxidative stress, were each shown to result in Ca2+ overload, an event that promotes cell death and endothelial dysfunction." (PMID 40996861, 2025).
fibrosis (3 papers, 2021 to 2022). the formation of excess fibrous connective tissue in an organ or tissue in a reparative or reactive process. "We evaluated cardiac fibrosis in response to pressure overload in Trpm4 cKO hearts and WT hearts by Masson’s trichrome staining." (PMID 34190686, 2021). "Furthermore, compared with that of the MG-NAFL, MG-NASH, and MG-fibrosis mice, the TRPM4 mRNA expression of the GXZY-NAFL, GXZY-NASH, and GXZY-fibrosis mice was decreased." (PMID 34887931, 2021). "Interestingly, it was recently shown that Trpm4 gene disruption, specifically in cardiomyocytes, results in a reduction in ventricular fibrosis induced by transverse aortic constriction in mice, indicating that TRPM4 also participates in cardiac fibrosis through those cells." (PMID 36139640, 2022). "When compared with an average 3.17-fold increase (p<0.001) in cardiac fibrosis in WT TAC hearts, the increase in Trpm4 cKO TAC hearts was only 1.75-fold (p<0.05)." (PMID 34190686, 2021). "The Western blotting results of the liver tissue proteins showed that TRPM4 protein expression levels of MG-NAFL, MG-NASH, and MG-fibrosis mice were significantly increased, indicating that liver damage persisted in the mice." (PMID 34887931, 2021). "Compared with those of the CG-NAFL, CG-NASH, and CG-fibrosis mice proteins, the MG-NAFL, MG-NASH, and MG-fibrosis mice protein bands were darker and thicker, suggesting that TRPM4 protein expression was abnormally increased in NAFLD." (PMID 34887931, 2021).
insulinoma (3 papers, 2017 to 2022). "TRPM4-mediated current was greatly reduced in the rat insulinoma cell line INS-1 expressing the ΔN-TRPM4 variant, and glucose- or arginine-vasopressin-induced insulin secretion was also lower." (PMID 35056138, 2022). "The inhibition of insulin secretion from rat islets by 9-phenanthrol is consistent with the roles of the TRPM4 channel in mediating electrical activity and insulin secretion that has been demonstrated in several rodent insulinoma cell lines." (PMID 29098165, 2017). "TRPM4 is present in human β-cells, rodent islets, and a variety of rodent insulinoma cells." (PMID 32168890, 2020). "It is expressed, together with the TRPM4, in rodent islets and rodent insulinoma cell lines." (PMID 32168890, 2020).
psoriasis (3 papers, 2021 to 2024). An autoimmune condition characterized by red, well-delineated plaques with silvery scales that are usually on the extensor surfaces and scalp. "Overexpression, gain of function, and activation of channels, including nAChR, TRPV1, TRPV3, TRPV4, TRPM4, and ANO1 in keratinocytes, as well as TRPV1, nAChR, Kv1.3, and KCa3.1 in immune cells, have been associated with the induction of psoriasis." (PMID 38474002, 2024). "We previously reported two gain-of-function (GoF) mutations of TRPM4 as the cause of progressive symmetric erythrokeratodermia (PSEK), which shares similar clinical and histopathological features with psoriasis." (PMID 36341417, 2022). "Firstly, to determine if TRPM4 is expressed in psoriasis skin, we analyzed a publicly available RNA sequencing dataset and found that TRPM4 was expressed in both psoriasis skin lesions and healthy skin controls (Gene Expression Omnibus GSE117405)." (PMID 36341417, 2022). "TRPM4′s mRNA level was smaller in peripheral blood-derived mononuclear cells of patients suffering from psoriasis than in cells from healthy subjects, indicating the possible role of TRPM4 in the pathogenesis of psoriasis." (PMID 35056097, 2021). "Overall, these data indicate that TRPM4 may contribute to PsD in humans and that it warrants further study as a target in human psoriasis." (PMID 36341417, 2022). "Our results further suggest a possible therapeutic application of TRPM4 inhibitors in psoriasis." (PMID 36341417, 2022). "Since both WT and Het TRPM4 mice had reduced PsD when treated with glibenclamide, we suggest that TRPM4 may be a new and relevant target for psoriasis in humans." (PMID 36341417, 2022). "Treatment with a TRPM4 inhibitor, glibenclamide, ameliorated the psoriasis induced by imiquimod in both wild-type and TRPM4I1029M mice, highlighting the potential therapeutic significance of TRPM4 targeting in the context of skin disorders." (PMID 38474002, 2024). "Specifically, peripheral blood mononuclear cells from individuals with psoriasis exhibit elevated expression of TRP channels such as TRPM2 and TRPV1 and decreased expression of TRPM4, TRPM7, TRPV3, TRPV4, and TRPC6." (PMID 38474002, 2024). "Thus, a known inhibitor of TRPM4 ameliorates PsD in TRPM4 mutant as well as WT mice, suggesting that TRPM4 may have a regulatory role in PsD and possibly introducing this protein as a therapeutic target in psoriasis." (PMID 36341417, 2022). "Thus, TRPM4 plays a critical role in regulating psoriasis-like features in mice, which possibly explains the resemblance of the skin lesions in PSEK patients to human psoriasis and may point to TRPM4 as a relevant target in psoriasis." (PMID 36341417, 2022).
acute myeloid leukemia (2 papers, 2021). Acute myeloid leukemia (AML) is a group of neoplasms arising from precursor cells committed to the myeloid cell-line differentiation. "The up-regulation of TRPM4, the only surface protein among up-regulated gene products in acute myeloid leukemia cell lines made TRPM4 a potential novel therapeutic target." (PMID 35056097, 2021). "TRPM4 expression also increased in those acute myeloid leukemia patients and acute myeloid leukemia cell lines where the MLL gene (a methyltransferase for histone H3 lysine 4) was rearranged." (PMID 35056097, 2021). "In acute myeloid leukemia (AML) patients and AML cell lines, expression of TRPM4 is significantly increased." (PMID 33562811, 2021).
acute pancreatitis (2 papers, 2021 to 2025). An acute inflammatory process that leads to necrosis of the pancreatic parenchyma. "As SOCE is essential to develop sustained and pathological elevation of [Ca2+]i and ORAI1 inhibitors were reported to mitigate the severity of acute pancreatitis, our data raise the possibility that TRPM4 plays a preventive role in the pathophysiology of Ca2+ signaling." (PMID 34329682, 2021).